ANO1 (anoctamin 1)
Diseases named in the same sentence as ANO1 in open-access papers (continued):
Sharing a sentence is not in itself a finding about the gene and the disease.
cancer (continued). "The ANO1 channel (TMEM16A) is involved in cancer cell proliferation, invasion, survival, and apoptosis; the signaling pathways that can be regulated by ANO1 include ERK, PI3K-Akt, TNF, Ca-M, and EGFR." (PMID 37408210, 2023). "Anoctamin 1 (ANO1) is upregulated in CRC and is associated with cancer development by activating the mitogen-activated protein kinase signaling pathway." (PMID 36505493, 2022). "ANO1, a Ca2+-activated chloride channel protein, is involved in cancer cell proliferation, cell cycle changes, cell migration, and metastasis." (PMID 36461044, 2022). "This article reviews the mechanism of ANO1 involved in the replication, proliferation, invasion and apoptosis of various malignant tumors." (PMID 35734591, 2022). "Recent studies have suggested ANO1 as a potential therapeutic target for several cancers, including OSCC." (PMID 34769467, 2021). "Most of the existing research provide complementary evidence on the contribution of ANO1 expression to cancer cell proliferative properties." (PMID 33803266, 2021). "Predictably, Ani9-5f decreased cancer cell viability at higher concentrations (25–50 μM), due to the more pronounced expression levels of ANO1 in GIST, compared to ANO1HIGH UT-SCC cell lines." (PMID 33803266, 2021). "Anticancer effects such as decreased cell viability due to downregulation of ANO1 are shown in these cancer cells." (PMID 34769467, 2021). "Previous studies revealed that inhibition of ANO1 can induce apoptosis through multiple signaling pathways including the NF-κB, TGF-β, CaMKII/MAPK and EGFR/MAPK signaling pathway in cancer cells expressing ANO1." (PMID 34769467, 2021). "ANO1 located on amplicon 11q13 is usually amplified in human cancers with poor prognosis and is pivotal in PDAC cell migration." (PMID 33731794, 2021). "As anticipated, Ani9-5f was more potent inhibitor as compared to its predecessor Ani9, which resulted in mild decrease of cancer cell viability and reduction of ANO1 protein levels." (PMID 33803266, 2021). "Taking into account comparison between healthy and cancer samples only in the case of ANO1 and TMEM173, we observed the same significant changes as in our data obtained from the TCGA." (PMID 34638224, 2021). "It plays an important role in the development of cancer; however, the role of ANO1 in NSCLC is unclear." (PMID 34281152, 2021). "ANO1 contributes to cancer development via the promotion of oncogenic signaling, including the EGFR and CAMK pathways." (PMID 34281152, 2021). "A number of previous studies have shown that inhibition or downregulation of ANO1 induces apoptosis in various cancer cell lines." (PMID 34769467, 2021). "Studies have shown that TMEM16A (also known as ANO1, DOG1, TAOS2, or ORAOV2) is associated with several cancer types." (PMID 34681590, 2021). "We demonstrated that ANO1-5f resulted in reduction of cancer cell viability and ANO1 protein levels in ANO1HIGH cells, as well as decrease in the expression of MCL1." (PMID 33803266, 2021). "Previous studies have reported that pharmacological inhibition of ANO1 inhibits the development of several carcinomas." (PMID 34281152, 2021). "Herein, we present our work on the preparation and biological evaluation of a novel series of pyrimidine derivatives as ANO1 inhibitors and anti-cancer effects." (PMID 33172169, 2020). "In fact, ANO1 (TMEM16A) was found to be located on human chromosome 11q13, and is frequently amplified in various types of malignant tumors." (PMID 33172169, 2020). "Previous reports suggest that ANO1 inhibitors can modulate cancer progression by downregulation of ANO1 in various cancer cells." (PMID 32899792, 2020). "Most of the findings on ANO1-dependent cell signaling have emerged from the cancer field; hence, the focus has been on mitogenic/survival signaling." (PMID 33250781, 2020).
cancer (continued). "Because it is involved in tumorigenesis, invasion, migration, and metastasis, the development of drugs that modulate the activity of ANO1 is of great interest in cancer treatment." (PMID 33172169, 2020). "However, the diagnostic capability of ANO1 mRNA in PBMCs for detection of cancer is unknown." (PMID 31266974, 2019). "Apart from ANO1, other members of the anoctamin family were also correlated with cell proliferation and cancer development, like ANO5 (TMEM16E), ANO7 (TMEM16G) and ANO9 (TMEM16J)." (PMID 30893776, 2019). "Another anion channel frequently upregulated in cancer is the Ca2+-activated Cl- channel TMEM16A, also called ANO1." (PMID 31544839, 2019). "ANO1 and its role in proliferation and cancer development has been reported repeatedly, but we are still far from any comprehensive understanding." (PMID 30893776, 2019). "Our results consistently suggest that ANO1 expression is required for the several aspects of cancer, such as increased cell migration and invasion." (PMID 31489251, 2019). "This can also be demonstrated in experiments using nanomolar concentrations of the recently identified potent ANO1 inhibitor niclosamide, which however, has a number of additional anti-cancer effects (c.f. below)." (PMID 30893776, 2019). "Silencing or inhibition of ANO1 suppresses proliferation, metastasis, and invasion of cancer cells, and also promotes GIST cells to undergo apoptosis." (PMID 29899325, 2018). "In tumorigenesis, it has been reported that ANO1 expression was associated with the proliferation, invasiveness, and apoptosis of cancer cells and inhibition of ANO1 suppressed the growth and progression of human cancer cells." (PMID 29416639, 2018). "Consistently, ANO1-mediated proliferation of cancer cells has been reported in various types of cancer cells." (PMID 29416639, 2018). "Chemical compounds inhibiting ANO1, such as CaCCinh-A01 and T16Ainh-A01 also inhibited proliferation and invasion of human cancer cells." (PMID 29416639, 2018). "As a therapeutic target of human malignant tumors, inhibition of ANO1 is under evaluation in various cancers." (PMID 29416639, 2018). "Recent studies showed that pharmacological or genetic downregulation of ANO1 significantly inhibited cancer cell proliferation, migration and invasion, even though the underlying mechanisms are still uncertain." (PMID 28362855, 2017). "While ANO1 expression negatively correlates with survival in several cancers, its epigenetic regulation is poorly understood." (PMID 29123240, 2017). "To investigate the effects of ANO1 on cell apoptosis of cancer cell lines, we carried out an ELISA assay to determine the amount of nucleosomes in the cytoplasmic fraction of cell lysates on the fourth day after lentiviral infection of ANO1 shRNAs." (PMID 27732935, 2016). "Evidence has also been reported for ANO1 involvement in cell proliferation, cell migration, and cancer progression." (PMID 27219012, 2016). "In summary, we have shown in this study that knockdown of ANO1 inhibits cell proliferation and induces cell apoptosis in different epithelium originated cancer cells that highly express ANO1 channels." (PMID 27732935, 2016). "Previous studies have shown that inhibition of ANO1 by small-molecule inhibitors reduce cancer cell proliferation, rotavirus-induced diarrhea, capsaicin-induced nocifensive behaviors, and contractile tone in vascular and airway smooth muscle." (PMID 27219012, 2016). "Analysis of patient data revealed a prognostic and predictive value of CLCA2 and ANO1 mRNA abundance in CTCs for lung and gastrointestinal cancer, respectively." (PMID 27618016, 2016). "Anoctamin-1 (ANO1) acts as a Ca2+-activated Cl− channel in various normal tissues, and its expression is increased in several different types of cancer." (PMID 27212225, 2016).
cancer (continued). "The protein expression of ANO1 was also detected by Western blot, and quantitative analysis showed about 6-fold elevation in HaCaT and four cancer cell lines, as compared with MCF 10A and BEAS-2B cells." (PMID 27732935, 2016). "Because the previous investigations on ANO1 in cancer have a limit to measure channel activity, therefore, we cannot differentiate between overall increase in channel expression and increased channel activity in tumors." (PMID 26811235, 2016). "Our findings show that ANO1 overexpression promotes cancer cell proliferation and migration; and genetic or pharmacological inhibition of ANO1 induces apoptosis and cell cycle arrest at G1 phase in different types of epithelium-originated cancer cells." (PMID 27732935, 2016). "ANO1 also promotes cancer progression by stimulating the cell proliferation signaling pathway involving EGFR and calmodulin-dependent protein kinase II (CAMKII) in breast cancer cells." (PMID 27212225, 2016). "ANO1, a calcium-activated chloride channel, has been reported to be amplified or overexpressed in tissues of several cancers." (PMID 27732935, 2016). "The growing evidence of the role of ANO1 in cancer has been suggested before its molecular identity was discovered." (PMID 26811235, 2016). "Based on reports of ANO1 overexpression in various types of cancers, it is likely that ANO1 is important for cancer development and metastasis." (PMID 27212225, 2016). "To investigate the biological function of ANO1, we started detecting the expression levels of ANO1 in several normal and cancer cell lines." (PMID 27732935, 2016). "Recent evidence suggests ANO1 involvement in cell proliferation, cell migration, tumorigenesis and cancer progression." (PMID 26196390, 2015). "The bidirectional interplay of EGFR and ANO1 highlights the importance of the functional complex formed between both proteins in regulating proliferation of cancer cells." (PMID 25823819, 2015). "We found some drug-like compounds and natural products showing potent ANO1 inhibitory activity, and investigated the effect of the hit compounds on growth inhibition of cancer cell lines, which express ANO1 endogenously." (PMID 26196390, 2015). "CaCCinh-A01 is also known to inhibit ANO1 (synonymously, TMEM16A), a calcium-activated chloride channel, which is expressed and amplified in human cancers." (PMID 26540279, 2015). "In contrast, ANO1 protein expression was only detected in severe dysplasia/carcinoma in situ (CIS) and at a much lower frequency than gene amplification." (PMID 26498851, 2015). "It has been reported that Ano1 is expressed in 2 (28.6%) of 7 cancer-adjacent normal breast tissues." (PMID 25961581, 2015). "ANO1 is located on the amplicon 11q13 that is frequently amplified in human cancers with poor prognosis." (PMID 25163766, 2015). "Taken together, these results demonstrate that ANO1 regulates EGFR-protein levels in cancer cells by a posttranslational, degradation-independent mechanism, suggesting a role of ANO1 in stabilizing EGFR in the cells." (PMID 25823819, 2015). "ANO1/TMEM16A has recently been shown to be highly expressed in several epithelium originated carcinomas." (PMID 26305547, 2015). "ANO1, a calcium-activated chloride channel, is highly expressed and amplified in human cancers and is a critical survival factor in these cancers." (PMID 24599954, 2014). "Our data demonstrate that inhibition of ANO1 activity is not sufficient to inhibit proliferation of ANO1-amplified cell lines, indicating that both ANO1 channel activity and ANO1 protein are required for its role in cancer." (PMID 24599954, 2014). "Only expression of ANO1 (in cancer cells and in the nuclei of cancer cells) was significant in multivariate analysis." (PMID 24988459, 2014).
cancer (continued). "In summary, our data demonstrate that inhibition of the channel activity of ANO1 is not sufficient to inhibit ANO1-dependent cell proliferation, indicating that the role of ANO1 in cancer only partially depends on its function as a channel." (PMID 24599954, 2014). "So far, ANO1 overexpression has been widely considered capable of enhancing proliferation and migration of cancer cells." (PMID 24639373, 2014). "ANO1 is an important oncogenic survival factor in these cancers, and RNAi-mediated knockdown of ANO1 in Te11 (HNSCC) and FaDu (ESCC) cells diminished cell proliferation." (PMID 24599954, 2014). "To further investigate the dual role of ANO1 in cancer, we generated CaCCinh-A01-resistant Te11 cell pools by culturing the cells in 10 μm CaCCinh-A01 (∼4-fold IC50) for >3 months." (PMID 24599954, 2014). "The closely related Ano1 has been shown to be upregulated in many cancers and it possesses CaCC activity, which stimulates cell proliferation." (PMID 24663380, 2014). "ANO1 overexpression frequently occurs in the cancer tissues along with 11q13 chromosome amplification." (PMID 24639373, 2014). "Our results provide an impetus for gaining a deeper understanding of ANO1 modulation in cells and introduce a new targeting approach for antitumor therapy in ANO1-amplified cancers." (PMID 24599954, 2014). "Poor prognosis of many types of cancers has been closely correlated with ANO1 gene amplification and protein overexpression." (PMID 24639373, 2014). "TMEM16A (ANO1) is a Ca2+-activated Cl− channel that is overexpressed in several carcinomas where it controls cell proliferation, migration and metastasis." (PMID 24493757, 2014). "Because the present data demonstrate a correlation between expression of Ano1 and cancer, we examined possible effects of Ano1-knockdown on proliferation of BHY cells, using three different siRNAs." (PMID 22912841, 2012). "Our study highlights that understanding the roles of ANO1 in cancer metastasis will be important in the rational design of drugs for this important class of targets." (PMID 20664600, 2010). "RNA-seq analysis were performed in cancer cells bearing different status of ANO1 and KRAS." (PMID 40396170, 2025). "Other genes, such as RYR2 and ANO1, both related to KRAS Signaling in the MSigDB “Hallmark Gene Sets”, were proposed for the hallmark of “Sustaining Proliferative Signaling”, underscoring their role in uncontrolled cell proliferation, a hallmark of cancer." (PMID 40136626, 2025). "Consequently, understanding the pathways through which TMEM16A impacts malignant transformation is crucial for the development of targeted therapies for cancers with increased ANO1 expression." (PMID 40707942, 2025). "Aminooctylamine (ANO1) plays an oncogenic role in various cancers." (PMID 38352864, 2024). "Inhibition of ANO1 in these cancer cells exhibits anticancer effects." (PMID 38892219, 2024). "Pharmacological inhibition of ANO1 inhibits the growth of various types of cancer cells." (PMID 38659592, 2024). "Additionally, ANO1 is highly expressed in breast, ovarian, and hepatocellular carcinomas and promotes the malignant biological behavior of cancer cells." (PMID 38352864, 2024). "Notably, ANO1-mediated resistance to immunotherapy involves the induction of TGF-β production, recruitment of cancer-associated fibroblasts (CAFs), and the subsequent formation of an immunosuppressive milieu." (PMID 38562143, 2024). "Pharmacological inhibition of ANO1 inhibits the growth of various cancer cell types." (PMID 37274097, 2023). "Its role and regulation seem to be tissue-dependent as inhibition of ANO1 was shown to suppress proliferation and/or migration and metastatic spread in various cancer cells and in mouse xenograft models in several studies, while having no or opposite effect in some other models." (PMID 37749499, 2023). "ANO1 also promotes cancer progression by stimulating the signaling pathway of cell proliferation." (PMID 36935741, 2023).
cancer (continued). "Comparable to the results in immunodeficient human cancer CDXs, ANO1 knockdown reduced the growth of CT26 CDXs, paired with increased CD8/granzyme B and decreased PD‐L1 IHC staining in xenograft tumors, suggesting a higher infiltration of cytotoxic CD8+ T cells in TIME." (PMID 37341301, 2023). "Although the exact role of anoctamin-1 in cancer is unknown, it participates in cancer proliferation and migration by modulating the activity of the MAPK, CAMKII, and EGFR signaling pathways." (PMID 37749499, 2023). "Similarly, luteolin, an ANO1 inhibitor, displays anticancer effects through the downregulation of ANO1 in cancer cells." (PMID 37274097, 2023). "However, considering that CaCCinh-A01 and DES are non-selective CaCC inhibitors, it cannot be concluded that the reduced EGFR signalling and anti-cancer effects are due to reduced ANO1 current activity." (PMID 36497413, 2022). "Inhibition of TMEM16A/ANO1 function reportedly suppresses cancer cell proliferation and migration." (PMID 35207106, 2022). "ANO1 can be used as a promising biomarker for detecting certain malignant tumors." (PMID 35734591, 2022). "This evidence suggests that ANO1 expression may play a significant role in promoting the activation of various cell surface receptors on cancer cells that are required for intracellular signalling and cell growth." (PMID 36497413, 2022). "In the present study, we have identified a novel and potent natural product, cinobufagin, as a potential therapeutic agent for OSCC which may have anticancer effects on other cancers that target ANO1." (PMID 34769467, 2021). "Notably, downregulation of ANO1 potently reduced the cell proliferation, metastasis and invasion in several cancer cells." (PMID 34769467, 2021). "Relative to the normal esophageal epithelium, 392 (46.3%) and 494 (52.1%) cancer-specific SEs were recovered in the EC and LNC H3K27ac profiles, respectively, and these SEs were enriched with cancer-associated genes or oncogenes, such as CCND125,26, CWH43, ANO1, and CXCR4." (PMID 34294701, 2021). "Our data demonstrate that ANO1 expression facilitates the expression of MCL1 and regulates the expression, subcellular distribution and proteolytic degradation of p27Kip1, which may explain how ANO1 mediates cancer cell progression." (PMID 33803266, 2021). "This pathway is known to be involved in enhanced ANO1 expression in several forms of cancer." (PMID 34488544, 2021). "ANO1 downregulation, on the other hand, allows p27Kip1 accumulation to occur in the absence of TRIM21, thereby causing a p27Kip1-dependent G1 arrest in a similar manner as previously observed in the case of HeLa cancer cells." (PMID 33803266, 2021). "Pharmacological inhibition of ANO1 reportedly induces apoptosis in various cancer cells." (PMID 34281152, 2021). "Therefore, it is possible that the downregulation of ANO1 by cinobufagin acted as an important anticancer mechanism in these cancer cells." (PMID 34769467, 2021). "In addition, several mechanisms of cancer development are related to ANO1, such as the EGFR-mediated AKT/SRC/ERK1/2 or Ras-Raf-MEK-ERK1/2 pathways; nonetheless, the underlying mechanism is unclear in NSCLC." (PMID 34281152, 2021). "On the other hand, genes negatively correlated with ANO1 were involved in cellular response to stress and external stimuli, which may favor further DNA damage and thus contribute to cancer progression." (PMID 34638224, 2021). "Recently, some research groups have studied whether expression changes of ANO1 in several cancers and other disease models are responsible for alterations of AKT and ERK signaling." (PMID 34281197, 2021). "Copy number amplifications are frequently observed in the chromosomal region 11q13, which harbors besides ANO1, genes CCND1, ORAOV1, PPFIA1, FADD and CTTN, the expression of which is associated with cancer proliferation, migration, apoptosis or poorer prognosis." (PMID 33803266, 2021).